IL1B (interleukin 1 beta)
Diseases named in the same sentence as IL1B in open-access papers (continued):
Sharing a sentence is not in itself a finding about the gene and the disease.
disc degeneration (continued). "Infiltrating immunocytes such as macrophages can release IL-1β into the extracellular space, where it activates matrix metalloproteinases (MMPs) that can degrade collagen and proteoglycan components of the nucleus pulposus (NP) matrix, leading to disc degeneration." (PMID 33391467, 2021). "In a rat model of disc degeneration, IL-1β stimulation increased RANKL mRNA expression; however, RANKL exerted catabolic effects only in the presence of IL-1β." (PMID 40806719, 2025). "Rapamycin treatment decreased the gene expression of MMP-3, MMP-13, IL-1β, IL-6, TNF-α, and protein levels of P16 and P21 in bleomycin-treated AFSCs suggesting that potential of rapamycin for disc degenerative diseases." (PMID 40727644, 2025). "During disc degeneration, immune cell infiltration leads to the release of pro-inflammatory cytokines such as tumor necrosis factor-alpha (TNF-α), interleukins IL-1β, IL-6, and IL-17, initiating and perpetuating a degenerative cascade." (PMID 40806719, 2025). "Recent research highlights how immune cells such as macrophages, T cells, and B cells, along with cytokines like IL-1β, TNF-α, and IL-6, play dual roles in both exacerbating and potentially mitigating disc degeneration." (PMID 40688090, 2025). "Pro‐inflammatory M1 macrophages exacerbate disc degeneration by amplifying inflammatory cytokines (e.g., TNF‐α, IL‐1β), promoting cellular senescence, and stimulating abnormal angiogenesis and neural ingrowth." (PMID 40371270, 2025). "On the contrary, we recorded significantly increased endogenous expression levels of inflammatory cytokines and their receptors such as IL-1β/IL-1 R and TNF-α/TNF-α R1, where their levels increased with severity of disc degeneration." (PMID 39286594, 2024). "IL-6, IL-1β and TNF-α show high levels in LDH, and their expression levels are affected by age and the degree of disc degeneration." (PMID 38268042, 2024). "Interleukin 1β (IL1β) and tumor necrosis factor‐α (TNF‐α) are proinflammatory cytokines known to be key mediators in the development and progression of disc degeneration and low back pain." (PMID 35106811, 2022). "IL-1β induces more cyclooxygenase-2 (COX-2) expression, thus forming a vicious cycle and exacerbates disc degeneration." (PMID 36457130, 2022). "To study the role of ASICs in the process of disc degeneration, we first examined the mRNA expression and protein levels of ASICs and NLRP3 inflammasome components such as NLRP3, caspase‐1, and IL‐1β in normal and degenerated disc tissues." (PMID 33111436, 2021). "Meanwhile, other researchers have identified that the levels of IL-1β, IL-6, IL-17, and TNF-α have a positive relationship with the degree of disc degeneration." (PMID 34308759, 2021). "In disc degeneration, AKT is phosphorylated, and activated in NPCs, which was realized by the several inflammatory responses, including IL-1β, IL-6, and TNFα." (PMID 32526705, 2020). "Recent studies have shown early-onset disc degeneration in progranulin and IL-1ra knockout mice implying the importance of endogenous TNF-α and IL-1β inhibitors in the maintenance of disc health." (PMID 30584238, 2018). "During disc degeneration, it has been demonstrated that IVD cells secrete proinflammatory cytokines such as TNF‐α, IL‐1α, IL‐1β, IL‐6, and IL‐17." (PMID 31463438, 2018). "Immunohistochemistry staining demonstrated that the levels of TNF-α, IL-1β and MMP-13 were increased in the pathogenesis of intervertebral disc disease." (PMID 28498809, 2017). "TNF-α and IL-1β exacerbate LDH inflammatory processes, and are believed to be key players during disc degeneration." (PMID 28498809, 2017). "IL-1β, an important inflammatory factor in disc degeneration, induces excessive apoptosis of disc cells, and this exacerbates the activation of the Wnt, MAPK, and MMP pathways, further advancing disc degeneration." (PMID 39623712, 2025).
disc degeneration (continued). "The release of IL-1β not only promotes the expression of more inflammatory cytokines but also further activates the NF-κB and MAPK signaling pathways through a positive feedback mechanism, exacerbating disc degeneration." (PMID 40688090, 2025). "Statistically significant increased expression of IL-1β, IL-6, IL-17, VEGF-A and CD31 was evident in the samples of the DDD group compared with the controls, that showed a strong correlation with the histological disc degeneration stage." (PMID 37626681, 2023). "It was shown that disc degeneration could produce a large number of inflammatory factors, such as TNF-α and IL-1β." (PMID 35855812, 2022). "Although IL-1β is proved to be able to induce disc cell apoptosis and disc degeneration, the expression of Smad7 in the AF cells under IL-1β stimulation has never been described." (PMID 35795857, 2022). "IL-1β-induced expression of MMP-3 through nuclear factor-kappa B (NF-kB), mitogen-activated protein kinase (MAPK) and syndecan 4 results in inflammation-mediated disc degeneration." (PMID 36613651, 2022). "In this study, we examined the contributions of secretory autophagy to disc degeneration in human and rat and tested whether MR409 can inhibit secretory autophagy-based IL-1β secretion and ensuing inflammation in vitro and as well as in aged mice." (PMID 33391467, 2021). "Activation of secretory autophagy in degenerated discs and induction of IL-1β release under oxidative stress suggested that ROS and TRIM16/LC3B reducer, such as MR409, may be effective against disc degeneration." (PMID 33391467, 2021). "Second, human IVD samples with different MRI grades of disc degeneration were utilized in this study; therefore, a potential bias regarding the gene expression of RANK/RANKL/OPG and the response of IL-1β, RANKL, OPG or ahRANKL-mAb may exist." (PMID 31101043, 2019). "This nontraumatic model of disc degeneration, based on the use of inflammatory cytokines IL-1β and TNF-α, mimics known gene expression patterns observed in the degenerative human disc." (PMID 24171898, 2013). "Whereas IL-1β is upregulated with disc degeneration, IL-1ra is not, resulting in an imbalance between catabolic and anabolic signaling." (PMID 22863285, 2012). "In addition, factors such as IL-1β, MAPK14, MMP9, and MMP3 can contribute to inflammation and matrix degradation, potentially further interacting with Wnt signaling to exacerbate disc degeneration." (PMID 39623712, 2025). "Analysis from mouse NP tissues shows sufficient quantities of RNAs, purity of the NP fraction, and overall RNA quality for gene expression studies, and reveals no increase in expression of disc degeneration markers, including TNFa, IL1b, and Mmp1 up to 15 months of age in C57BL6 wildtype mice." (PMID 31891122, 2019). "Importantly IL‐1β and TNFα, regarded as key contributors to disc degeneration, were not shown to affect the NP cell differentiation of mesenchymal stem cells (MSCs) in the NPgel." (PMID 31463465, 2019). "Monolayer culture, which is different from the naive environment, may accelerate disc degeneration and may explain the gradual upregulation of the IL-1β gene in the control group (data not shown)." (PMID 27405858, 2016). "Other cytokines besides IL-1β (tumor necrosis factor (TNF)-α, IL-6, IL-8, prostaglandin E2 (PGE2), and nitric oxide (NO)) may also be involved in the complicated pathogenesis of disc degeneration, including upregulation of MMP genes." (PMID 27405858, 2016). "Indeed, in disc degeneration models using in vitro three-dimensional cultures, human annulus cells display increased expression of pro-inflammatory cytokines, such as IL-1β and TNF-α, while exposure to TNF-α and IL-1β resulted in significant downregulation of GDF-5." (PMID 32443833, 2020).
disc degeneration (continued). "Human AF cells isolated from IVD biopsies from patients with adolescent idiopathic scoliosis (AIS) or disc degeneration (DD) were exposed to physiological cyclic tensile strain (CTS) for 72 h in a custom-made device, with or without interleukin (IL)-1β medium supplementation." (PMID 35155408, 2021).
memory impairment (91 papers, 2012 to 2025). "In animals, persistent interleukin 1 beta (IL-1β) expression in the hippocampus also activates astrocytes and microglia for a strong inflammatory response and subsequently causes memory impairment." (PMID 37600508, 2023). "A peripheral surgery-induced innate immune responses and consequent release of inflammatory cytokines can trigger an IL-1β-mediated neuroinflammatory process that underlies memory impairment." (PMID 37735415, 2023). "A correlation between neuroinflammation and memory impairments has been proposed, as the levels of proinflammatory molecules such as IL-1 and IL-1β in the brain are associated with AD and AIDS-mediated dementia." (PMID 35841100, 2022). "In mouse models, IL-1β concentrations have been linked not only to neurodegenerative diseases but also to memory impairment and anxiety disorders." (PMID 32377159, 2020). "Increased serum levels of inflammatory cytokines postoperatively are associated with memory impairment, reactive microgliosis, and upregulated interleukin (IL)-1β expression in the hippocampus." (PMID 29137628, 2017). "Memory impairment caused by surgery intervention is related to the increased levels of plasma cytokines and the hippocampal neuron IL-1β pathway." (PMID 29137628, 2017). "IL-6 had facilitating effects on IL-1β in mediating inflammation and causing hippocampal-dependent memory impairment." (PMID 24236147, 2013). "A recent study showed that tibial surgery under general anesthesia triggered an IL-1β-mediated inflammatory process in the hippocampus that underlies memory impairment in young adult mice." (PMID 23613842, 2013). "Besides, IL-6 promotes IL-1β mediated inflammatory responses that cause hippocampus-dependent memory impairment." (PMID 38082215, 2023). "Because AβOs have been shown to trigger an increase in brain IL-1β levels, we hypothesized that abnormal activation of this pro-inflammatory pathway could lead to synapse loss and memory impairment via alterations in mitochondrial dynamics." (PMID 33612100, 2021). "The observed lead‐induced increase in the concentration of TNF‐α and IL‐1β may be associated with the induction of neuroinflammation‐induced memory impairment." (PMID 34087957, 2021). "Previous studies showed that pro-inflammatory cytokines, such as TNFα, IL6, and IL1β, could potentially disturb the Aβ clearance and cause memory impairments." (PMID 32867800, 2020). "In addition, IL-6 facilitates the effect of IL-1β in mediating inflammation and causing hippocampal-dependent memory impairment." (PMID 29137628, 2017). "Our results showed that anesthesia and surgery induced significant hippocampus-dependent memory impairment, which was accompanied by PV interneuron phenotype loss and increased expression of interleukin-1β (IL-1β), markers of oxidative stress and NADPH oxidase 2 (Nox2) in the hippocampus." (PMID 27790135, 2016). "Memory impairment; notable neuroinflammation, including astrocyte and microglial activation; and elevated protein levels of IL‐1β, TNF‐α, and IL‐6 in the hippocampus were detected in the Pg and Pg OMV groups." (PMID 39932228, 2025). "An early preclinical study in mice models of orthopedic surgery showed that due to peripheral surgery, the hippocampus experiences an IL-1β-mediated inflammatory response, resulting in memory impairment and the pathogenesis of POCD." (PMID 38912522, 2024). "In animal experiments, sustained expression of interleukin-1 beta (IL-1β) in the hippocampus can activate astrocytes and microglia to trigger a robust inflammatory response, ultimately leading to memory impairment." (PMID 36935511, 2023). "When CBS is knockout, IL-1β-induced synapse reduction and memory impairment are significantly alleviated." (PMID 37492730, 2023). "This study provides a new explanation for inflammation-induced memory impairment: IL-1β through the S-sulfhydration of GAPDH by H2S leads to the combination of GAPDH and Siah and increases the stability of Siah." (PMID 37492730, 2023).
memory impairment (continued). "For instance, the activation of NLRC4 inflammasome interacts with CASP1, IL-1β, and p-Tau to contribute to neuroinflammation and memory impairment." (PMID 35783533, 2022). "NLRC4 inflammasome, via IL-1β and IL-18, contributes to memory impairment and neuroinflammation in a rat model of Alzheimer-like disease." (PMID 33584697, 2020). "IL1-β increase in AD is believed to be correlated with memory impairments, and to promote neuronal and synaptic dysfunction." (PMID 32050445, 2020). "We showed that treatment with IFNβ1a was able to reverse memory impairment and to counteract microglia activation and upregulation of pro-inflammatory cytokines (IL-6, IL-1β) in the hippocampus of Aβ1-42-injected rats." (PMID 30777084, 2019). "What is more, recent studies have identified that specific inhibition of IL-1β, both in mice pretreated with IL-1 receptor antagonist and in IL-1R–/– mice, alleviated the neuroinflammatory effects of operation and memory impairment." (PMID 31814872, 2019). "For example, it has been demonstrated that the release of TNF-α and IL-1β is a sign of neuroinflammatory-induced memory impairment." (PMID 31231221, 2019). "The short treatment with IFNβ1a was able to reverse memory impairment and to suppress microglia activation and the upregulation of pro-inflammatory cytokine (IL-6, IL-1β) levels and oxidative stress in the hippocampus." (PMID 30777084, 2019). "It has been reported that chronic administration of scopolamine for 14 days increased the expression of pro-inflammatory factors such as IL-1β and TNFα and inflammation is a proposed mechanism for scopolamine-induced memory impairment." (PMID 29942435, 2018). "Previous DIO animal models have also demonstrated an association between HFD consumption and elevated neuroinflammatory markers, such as TNF-α and IL-1β, following demonstrated memory impairments on the T-maze and Y-maze." (PMID 30619085, 2018). "Inflammatory cytokines, including IL-6, IL-1β, and TNF-α, have been reported to be associated with learning and memory impairment." (PMID 28373844, 2017). "Blocking these exaggerated effects, specifically by decreasing the release of tumor necrosis factor α (TNF-α), interleukin 1β (IL-1β), and interleukin 6 (IL-6), has been shown to prevent inflammation-induced memory impairment." (PMID 29167670, 2017). "Prevention of the IL-1β increase, e.g., by inhibiting IL-1β synthesis or by administration of an IL-1 receptor antagonist, averted the memory impairments." (PMID 27555812, 2016). "Our previous studies showed that GBE50 prevented age-related learning and memory impairment and reduced the expression of several proinflammatory cytokines, including IL-1β and IL-6, in hippocampal cells." (PMID 24782908, 2014). "LPS also successfully induced memory impairment in the Y maze test, neuroinflammatory responses, and oxidative stress such as increases in mRNA levels of interleukin (IL)-1β and IL-6, heme oxygenase-1, microglial activation, and iNOS activity in hippocampus." (PMID 24999480, 2014). "We previously showed that intravenous lidocaine infusion significantly attenuated the learning and memory impairment and IL-1β production in the hippocampus of rats after isoflurane anesthesia only." (PMID 24884762, 2014). "Furthermore, rutin modulates the production of pro-inflammatory cytokines by decreasing TNF-α and IL-1β generation in microglia and enhances the memory in scopolamine-induced memory impairment in zebrafish by enhancing cholinergic neurotransmission." (PMID 41471791, 2025). "Hippocampal injection of agomir reduced IL-1β and reversed memory impairment." (PMID 41454181, 2025). "We show that nVNS pre-treatment suppresses CHI-associated spatial learning and memory impairment and prevents IL-1β activation in injured neurons, but not endothelial cells." (PMID 38435077, 2024).
memory impairment (continued). "IL-1β secreted by activated microglia can suppress axonal development and synapse formation through activation of the p38-MAPK signaling pathway associated with memory impairments in septic patients." (PMID 39497013, 2024). "Additionally, IL-1β participates in the induction of memory impairment, as well as in the release of CRH." (PMID 37189795, 2023). "Looking for a correlation between the increased hippocampal levels of IL-1β and memory impairment observed in HSV-1-infected mice, we treated animals with Anakinra, a pharmacological inhibitor of IL-1R, already used to treat chronic or acute inflammatory diseases." (PMID 37261502, 2023). "Collectively, these data support our hypothesis that neuroinflammation mediated by IL-1β affects mitochondrial dynamics and memory impairment in mice." (PMID 33612100, 2021). "IL-6, IL-1β, and TNF-α have been reported to be associated with learning and memory impairment." (PMID 28373844, 2017). "In this context, it has been described that the long-term maintenance of high IL-1β levels, particularly in the hippocampus, may be responsible for hippocampal-dependent memory impairments observed in aging rats." (PMID 25874023, 2015). "The role of IL-1β and IL-6 in surgery-induced learning and memory impairment has been indicated." (PMID 24884762, 2014). "In addition, experimental animal studies show that centrally administered IL-1β reduces acetylcholine (Ach) release from the hippocampus, which coincided with memory impairment." (PMID 24376764, 2013). "Thus, IL-1β acts as a key switch during memory impairment in SAE rats." (PMID 35111693, 2021). "Indeed, acute inflammation induced by LPS or IL-1β infusion led to memory impairment." (PMID 31231221, 2019). "The real-time quantitative PCR analysis of the expression of Pik3r5, Il-1β, and Slc18a2 further indicated that these three genes were all the key factors in the effects of Cordyceps polypeptide on the nervous system in the mouse model of learning and memory impairment." (PMID 29736181, 2018). "In this review, we highlight some studies in which cytokines (e.g., IL-1β, CCL-3) were injected directly into the brain parenchyma, inducing memory impairment." (PMID 40352932, 2025). "Our results revealed a two-fold increase in IL-1β and TNF-α levels in RSD mice, suggesting synergism in the hippocampus, thus inducing memory impairments." (PMID 36278007, 2022). "Salidroside potentially reduces hippocampus-dependent memory impairment by reducing Aβ1-42 deposition, microglial activation, and expression of proinflammatory factors, such as TNF-α, IL-6, and IL-1β, in the brain." (PMID 36014776, 2022). "In physiological concentrations, IL‐1β enhances hippocampal LTP and memory function, whereas, in pathological concentrations, it suppresses LTP and induces memory impairment." (PMID 34042283, 2021). "In this study, we observed that melatonin treatment reduces the over‐production of IL‐1β and TNF‐α, and prevents neuroinflammation and memory impairment in the lead‐induced experimental rats." (PMID 34087957, 2021). "Mice in the laparotomy group displayed memory impairment up to POD 14 with initial high levels of inflammatory cytokines in the liver, frontal cortex (IL-1β, IL-6, and TNF-α), and hippocampus (IL-1β and IL-8)." (PMID 29776428, 2018). "Microglial activation stimulates the accumulation of pro-inflammatory cytokines, such as IL-1β, IL-6, and TNF-α, which are responsible for memory impairment induced by LPS." (PMID 27803668, 2016). "It significantly modulated the oxidative stress markers (SOD, GSH, CAT, MDA, and NO), inflammatory cytokines (IL-6, IL-1β, TNF-α), neurotrophic factors (CREB, BDNF), apoptotic markers (NFkB, caspase-3, caspase-9), and neurotransmitters (NE, DA, and GABA) in METH-induced memory-impaired rats." (PMID 41010958, 2025).